FOXO3 (forkhead box O3)
Diseases named in the same sentence as FOXO3 in open-access papers (continued):
Sharing a sentence is not in itself a finding about the gene and the disease.
colorectal cancer (75 papers, 2013 to 2025). A primary or metastatic malignant neoplasm that affects the colon or rectum. "In addition, gene polymorphism of FOXO3 has been validated to influence various human disorders including cancer, such as pancreatic cancer, colorectal cancer, active tuberculosis, polycystic ovary syndrome, and acute lymphoblastic leukemia (ALL)." (PMID 38720807, 2024). "Likewise, the downregulation of FOXO3 is associated with poor outcomes in neuroblastoma, breast, and colorectal cancers." (PMID 32629884, 2020). "Studies focusing on FOXO3 localization in breast and colorectal cancers have shown that higher levels of FOXO3 nuclear localization correlate with lower overall survival." (PMID 38519029, 2024). "When the drug was applied to colorectal cancer cells, the expression of the transcription factor FoxO3 increased." (PMID 39668836, 2024). "FOXO3 inhibited cell proliferation and induced apoptosis in colorectal cancer by regulating BIM expression." (PMID 38720807, 2024). "Conversely, in glioblastomas, FOXO3 activation promotes differentiation of CSCs, suppressing their tumorigenicity, and in colorectal cancer, FOXO3 activation inhibits CSCs self-renewal by significantly inducing TRAIL and its receptor DR5." (PMID 37891184, 2023). "Studies on the role of FOXO3 in breast and colorectal cancer have revealed that high FOXO3 expression in the nucleus predicts poor prognosis." (PMID 34123834, 2021). "This study represents apoptotic potential of acetylshikonin against colorectal cancer cells via translocation of FOXO3 to the nucleus and upregulation of ROS generation." (PMID 33953834, 2021). "The knockdown of FOXO3 led to sustained CSC self-renewal in glioblastoma, prostate, liver, and colorectal cancers and female cancers; in contrast, leukemia-initiating cells require FOXO3 for stem cell survival." (PMID 33477367, 2021). "For example, a study examined colorectal cancer patients and found that FOXO3 expression was reduced in tumor tissue samples." (PMID 34968392, 2021). "Ectopic miR-153 in colorectal cancer mediated drug resistance by targeting forkhead box O3a (FOXO3a)." (PMID 34270461, 2021). "Reduced FOXO3 levels in colorectal cancer, esophageal squamous cell carcinoma (ESCC) and pancreatic ductal adenocarcinoma samples also correlated with more advanced disease." (PMID 34771514, 2021). "Acetylshikonin induces apoptosis in HCT-15 and LoVo human colorectal cancer cells via nuclear translocation of FOXO3 and ROS level elevation." (PMID 34452487, 2021). "The nuclear localization of both FOXO3 and β-catenin also correlate with increased metastasis in colorectal cancer." (PMID 32629884, 2020). "In a similar manner, the p38 MAPK is also activated by cetuximab to induce cell death and inhibit cell proliferation via FOXO3 in colorectal cancer." (PMID 32372224, 2020). "ONC201/TIC10 is a dual inhibitor of AKT and ERK that targets chemotherapy-resistant colorectal cancer stem cells via induction of TRAIL expression by FOXO3." (PMID 29299162, 2017). "Besides, FOXO3 also is regulated by miR-155 in colorectal cancer cells and by miR-372 in gastric cancer cells, and enhanced FOXO3 expression by Akt promotes cell survival and resistance." (PMID 35444536, 2022). "Moreover, ERK2 regulated the epithelial-to-mesenchymal transition (EMT) plasticity in breast epithelial cells through FoxO1 activation, and p38 activated by anticancer drugs affected colorectal cancer growth via the regulation of FoxO3 nuclear localization." (PMID 36077661, 2022). "In this study, we hypothesized that acetylshikonin induces apoptosis in colorectal cancer via activation of FOXO3 expression, thus the downstream apoptotic pathways." (PMID 33953834, 2021). "In addition, in renal carcinoma and colorectal cancer, the decreased expression of FOXO3 is important for metastasis." (PMID 32629884, 2020).
colorectal cancer (continued). "Similarly, FOXO3 upregulation is associated with poor outcomes in AML, glioblastoma, pancreatic ductal adenocarcinoma, and breast and colorectal cancers." (PMID 32629884, 2020). "FoxO3 has been shown as a mediator of cisplatin toxicity in colorectal cancer." (PMID 30646603, 2019). "FOXO3 has further been associated with MMP-9 activity and elevated invasion capacity in glioma, with increased cell migration and invasion in gastric and colorectal cancers." (PMID 31861249, 2019). "The knockdown of FOXO3 results in the increased CSC self-renewal capacity in prostate, glioblastoma, ovarian, breast, liver, and colorectal cancer, whereas leukemia needs FOXO3 for stem cell maintenance." (PMID 39201332, 2024). "Recent investigations have shown that ASH increases ROS and nuclear damage with a subsequent nuclear translocation of FOXO3 and induced caspase-dependent apoptosis in osteosarcoma U2OS, renal-cell carcinoma and colorectal cancer HCT-15, and LoVo cells." (PMID 36829578, 2023). "AARS2 and FOXO3 are protective factors in the prognostic model of CRC, and the former regulates the proliferation of colorectal cancer by affecting mitochondrial respiration." (PMID 36299603, 2022). "FOXO3-dependent MMP activity and elevated invasion/migration capacity has also been reported in glioma, in gastric cancer, and in colorectal cancer." (PMID 31861249, 2019). "Knockdown of FOXO3 results in increased CSC self-renewal capacity in prostate, glioblastoma, ovarian, breast, liver, and colorectal cancer; in contrast leukemia-initiating cells need FOXO3 for stem cell maintenance." (PMID 30728463, 2019). "One study of colorectal cancer reported that LAMB3 overexpression was activated by BRD2/acetylated ELK4 complex; furthermore, LAMB3 overexpression activated AKT and resulted in degradation of FOXO3/4, a tumor suppressor protein." (PMID 38473784, 2024). "Interestingly, miR-96 is found to promote colorectal cancer proliferation through targeting both FOXO1 and FOXO3, suggesting that there are common complementary sequences in FOXOs for miR binding." (PMID 32372224, 2020). "However, the anticancer effects of acetylshikonin in colorectal cancer via FOXO3 activation have not been well studied." (PMID 33953834, 2021).
ovarian carcinoma (69 papers, 2011 to 2026). A malignant neoplasm originating from the surface ovarian epithelium. "Moreover, low levels of FOXO3 protein expression have been associated with poor prognosis in several types of tumors, including ovarian cancer, hepatocellular carcinoma, gastric cancer, and lung adenocarcinoma." (PMID 31303978, 2019). "Tumor-associated macrophage (TAM)-derived EVs carry miR-29a-3p, which targets forkhead box O3 (FOXO3) and leads to increased programmed death-ligand 1 (PD-L1) expression in ovarian cancer cells." (PMID 40284522, 2025). "Chelidonium majus extract triggered apoptosis in SKOV3, OVCAR3, and MDAH2774 human ovarian cancer cells by increasing FOXO3 expression." (PMID 39334758, 2024). "Subsequently, we found that NEK6 knockdown inhibited FOXO3 S7 phosphorylation in chemoresistant ovarian cancer cells." (PMID 39256367, 2024). "The results showed that NEK6 was able to exert a direct interaction with FOXO3 in both chemosensitive and chemoresistant ovarian cancer cells." (PMID 39256367, 2024). "In summary, Har not only promotes autophagy by regulating the PI3K/AKT/mTOR/FOXO3 signalling pathway to play an anti-ovarian cancer role, but also promotes ferroptosis and pyroptosis in ovarian cancer." (PMID 38499622, 2024). "In conclusion, Har exerts its anti-ovarian cancer effect not only by promoting autophagy by regulating the PI3K/AKT/mTOR/FOXO3 signalling pathway but also by promoting ferroptosis and pyroptosis." (PMID 38499622, 2024). "For example, a study of ovarian cancer cells has shown that this protein, along with forkhead box O3 (FOXO3a) and hyperactive insulin-like growth factor-1-receptor (IGF1R), plays a very important role in the drug resistance of ovarian cancer cells." (PMID 35715750, 2022). "High levels of miR-29a-3p expression inhibit PD-L1 expression in ovarian cancer cells by downregulating the FOXO3-AKT/GSK3β axis, leading to immune escape of OC cells and ultimately promoting the proliferation of ovarian cancer cells." (PMID 36741380, 2022). "Another study highlighted that suppression of FOXO3 targeted by miR‐551b boosted cell proliferation, invasion, and cisplatin resistance of ovarian cancer." (PMID 33655712, 2021). "Recently, miR-551b was reported to promote ovarian cancer stem cell proliferation, invasion, and drug resistance, in part by suppressing FOXO3 expression." (PMID 31013711, 2019). "In ovarian cancer cells, the overexpression of phosphorylated FOXO3 at Thr-32 correlated with lymph node involvement." (PMID 25202904, 2014). "FOXO3 could activate the apoptotic signaling pathway, inducing cell cycle arrest in the nucleus of human ovarian cancer cells, while FOXO3 in the cytoplasm is unable to serve as a transcription factor." (PMID 40428322, 2025). "EGCG suppressed ovarian cancer cell growth and induced apoptosis by activating FOXO3." (PMID 39334758, 2024). "Butein inhibited cell growth in ovarian cancer by regulating the IL6/STAT3/FOXO3 pathway." (PMID 39334758, 2024). "Hence, CircEXOC6B accelerated cell sensitivity to PTX via decoying miR-376c-3p and upregulating FOXO3 in ovarian cancer." (PMID 38152652, 2023). "FOXO3 (forkhead box O3) was a potential target of miR-376c-3p in ovarian cancer cells." (PMID 38152652, 2023). "Members of the FOXO subfamily were previously shown to cooperate with SMAD2/3–SMAD4 to induce CDKN1A (also called p21Cip1) in epithelial cells in response to TGF-β, and FOXO3 has previously been shown to cooperate with the SMADs to regulate cyclin induction in ovarian cancer." (PMID 35302162, 2022). "Foxo3 interacts with mmu-miR-153-3p, which is known to suppress tumor growth in ovarian carcinoma." (PMID 34639162, 2021). "Our results demonstrated that CA125 via the MSLN/DKK1/SGK3/FOXO3 pathway accelerates cell migration, and targeting mesothelin may potentially be utilized in ovarian cancer therapy." (PMID 33613114, 2021).
ovarian carcinoma (continued). "Furthermore, irrespective of its role in cell invasion, LIN28B displays an antiapoptotic role in ovarian cancer cells through the regulation of the protein kinase Bβ (AKT2)/forkhead box O3a (FOXO3A)/Bcl-2-like 11 (BIM) axis." (PMID 32528950, 2020). "miR‐590‐3p targets CCNG2 and FOXO3 to promote ovarian cancer development." (PMID 32892482, 2020). "For instance, stimulation of leptin elicited signal transducers and activators of transcription-5 (STAT5)-mediated increase of miR-182 and miR-196, which were proven to target forkhead box O3 (FOXO3), thus leading to augmentation of ovarian cancer proliferation." (PMID 31408957, 2019). "The FOXO3 elevation could potentially invert the cisplatin resistance in ovarian cancer." (PMID 33655712, 2021). "Indeed, FOXO3 has a role in the regulation of genes involved in autophagy: in response to decreased glycolysis in colorectal and ovarian cancer cells, it first induces autophagy as an attempt to retain energy to survive, whereas it triggers autophagic cell death under persistent stress conditions." (PMID 31303978, 2019). "Interestingly, when we screened for small molecules that can promote the activation of FOXO3 in ovarian cancer cells, we identified auranofin as a candidate FOXO3-activating small molecule from the US Food and Drug Administration (FDA)-approved compound libraries." (PMID 25096914, 2014). "Namely, CA125 promotes the migration of ovarian cancer cells by reducing DKK1 expression and activating the SGK3/FOXO3 pathway." (PMID 33613114, 2021). "Taken together, these results suggest that miR-590-3p promotes ovarian cancer development, in part by directly targeting CCNG2 and FOXO3." (PMID 31013711, 2019). "Cancer drugs such as Imatinib (for the treatment of chronic myeloid leukemia), cetuximab, lapatinib, gefitinib (for the treatment of breast, prostate, kidney and ovarian cancers) also target both AKT and ERK in order to inhibit phosphorylation of FoxO3." (PMID 22489133, 2012). "Besides, exosomes enriched with miR-29a-3p mediate the FOXO3-AKT/GSK3β axis and improve the expression of PD-L1 in ovarian cancer cells, consequently promoting the proliferation and immune escape of ovarian cancer cells." (PMID 35741075, 2022). "Notably, in our study, FOXO3 S7 phosphorylation was mainly found in the cytoplasm, but not in the nucleus of ovarian cancer cells." (PMID 39256367, 2024).
gastric cancer (58 papers, 2013 to 2025). A primary or metastatic malignant neoplasm involving the stomach. "Activation of the FoxO member FoxO3 induces cell cycle arrest and promotes cell apoptosis in gastric cancer, pancreatic cancer, cervical cancer 60,61, while loss of FoxO3 is associated with poor prognosis in estrogen-dependent breast cancer." (PMID 35069908, 2022). "Higher methylation in the first exon region of FOXO3 (cg12664806) was associated with shorter survival from gastric cancer." (PMID 34943892, 2021). "The inhibition of the PI3K-AKT pathway by inhibitor treatment also suppressed the proliferation of FOXO3-Cyt gastric cancer cells, which was associated with the nuclear accumulation of endogenous FOXO3." (PMID 33795838, 2021). "Methylation at a CpG in the first exon region of FOXO3 (cg12664806, 6:108882981) was associated with survival from gastric cancer (per M-value standard deviation HR = 2.39, 95% CI: 1.60–3.56, p = 1.9 × 10−5)." (PMID 34943892, 2021). "We found that the nuclear accumulation of FOXO3 causes growth suppression in FOXO3-Cyt-type gastric cancer, indicating a tumor-suppressor role of FOXO3 in this type of gastric cancer." (PMID 33795838, 2021). "Methylation at a CpG in the first exon region of FOXO3 (6:108882981) was associated with gastric cancer survival (HR = 2.39, 95% CI: 1.60–3.56, p = 1.9 × 10−5)." (PMID 34943892, 2021). "In addition, we sought to examine the role of PLOD3 on mediating Trastuzumab resistance in gastric cancer and its underlying mechanism by investigating the involvement of FoxO3/Survivin pathway." (PMID 35835735, 2022). "Furthermore, the inhibition of the PI3K-AKT pathway led to the suppression of the survival and proliferation of FOXO3-Cyt-type gastric cancer cells, which is associated with the clear nuclear accumulation of FOXO3." (PMID 33795838, 2021). "PLOD3 decreases trastuzumab sensitivity by repressing FOXO3, resulting in the upregulation of Survivin protein in gastric cancer." (PMID 39068670, 2024). "has revealed that the IFITM3 can expand malignant progression, promote cancer stemness and chemoresistance of gastric cancer by targeting MET/AKT/FOXO3/c-MYC axis." (PMID 37304304, 2023). "In conclusion, we show that PLOD3 is a key mediator for HER-2 resistance through downregulating the expression of FoxO3 therefore upregulating Survivin pathway in gastric cancer." (PMID 35835735, 2022). "In our study, we show that PLOD3 is a key mediator for HER-2 resistance through downregulating FoxO3 therefore promoting survivin pathway in gastric cancer." (PMID 35835735, 2022). "It is therefore possible that treatment of FOXO3-Cyt-type gastric cancer with a PI3K-AKT inhibitor is effective for suppressing the survival or proliferation through the nuclear translocation of FOXO3." (PMID 33795838, 2021). "We further performed immunohistochemical analyses of FOXO3 using 15 lines of gastric cancer PDX tumors." (PMID 33795838, 2021). "A database analyses indicated that deletion of the FOXO3 gene was found in <1.6% of gastric cancers." (PMID 33795838, 2021). "In the FOXO3-Cyt gastric cancer cells, the expression of the constitutive active mutant FOXO3 (Act-ER FOXO3) induced the nuclear accumulation of FOXO3 and significantly suppressed colony formation and proliferation." (PMID 33795838, 2021). "We therefore examined the FOXO3 expression and subcellular localization in 50 human primary gastric cancer tissues by immunohistochemistry." (PMID 33795838, 2021). "Accordingly, the present results suggest that the inhibition of PI3K-AKT signaling and nuclear transportation of the endogenous FOXO3 are potential therapeutic strategies for FOXO3-Cyt-type gastric cancer." (PMID 33795838, 2021). "We did not detect any correlation between the FOXO3 localization and the malignancy stage; the FOXO3 expression and its subcellular localization therefore cannot be used as a prognostic marker for gastric cancer." (PMID 33795838, 2021).